MCL1 (MCL1 apoptosis regulator, BCL2 family member)
Diseases named in the same sentence as MCL1 in open-access papers (continued):
Sharing a sentence is not in itself a finding about the gene and the disease.
cancer (continued). "Several reports have shown that Mcl-1 promotes cell survival and targeting Mcl-1 via BH3-mimetic molecules can induce cell death in Cisplatin resistant cancer cells." (PMID 25409302, 2014). "In contrast, among 10 tumors (#1-10) from the same set of samples, the mRNA expression of its targets (EZH2, MCL-1 and FOS) was significantly higher in cancer tissues." (PMID 25153722, 2014). "Results show that TAI-1 induces cancer cell death through the induction of cleavage of apoptotic proteins Caspase 3 and PARP and degradation of anti-apoptotic proteins MCL-1 and suggests that TAI-1 leads to activation of the apoptotic pathways." (PMID 24401611, 2014). "Several potential anti-cancer agents, such as NVP-BKM120 (a PI3K inhibitor) and R-roscovitine (a cyclin-dependent kinase inhibitor), downregulated the levels of Mcl-1, enhancing TRAIL-induced apoptosis." (PMID 24566141, 2014). "High levels of Mcl-1 correlated with elevated USP9X expression in follicular lymphoma, diffuse large B-cell lymphoma, and some other cancer samples." (PMID 23431463, 2013). "The expression of DRs and proapoptotic (Bid, Bax, Bak, Smac/DIABLO) or antiapoptotic (FLIP, Bcl-2, Bcl-xL, Mcl-1, Akt, IAP-1, IAP-2, XIAP, survivin) proteins in cancer cells is involved in TRAIL-resistance." (PMID 23573148, 2013). "In this study, we focused on revealing mechanisms by which API-1 induces apoptosis of cancer cells and uncovered GSK3-dependent Mcl-1 degradation as a critical mechanism accounting for induction of apoptosis by API-1." (PMID 24261825, 2013). "Our selected model, the second model with Mcl-1, predicted that LY294002, LY294002 & C4BRaf, LY294002 & DNPAK1, LY294002 & DNPAK1 & C4BRaf should have similar effects on the percent apoptosis of cancer cells, which was consistent with the experimental data." (PMID 24339759, 2013). "In cancer cells, STAT5 activation lead to the increased expression of downstream target genes (Bcl-xL, mcL-1, cyclinD1 /D2 and c-myc), which increased cell proliferation, cell survival, angiogenesis, and immune system evasion." (PMID 23915238, 2013). "By reducing Mcl-1 levels, API-1 is able to induce apoptosis and sensitize cancer cells to TRAIL-induced apoptosis." (PMID 24261825, 2013). "In conclusion, our findings suggest that βArr1 and Mcl-1 are involved in the self-renewal and expansion of NSCLC-CSCs and are potential targets for anti-cancer therapy." (PMID 23418490, 2013). "The key findings from this study highlight the importance of the cellular context of different cancer cells for the function of multifunctional RBPs like SRSF1 and have implications for therapeutic approaches employed to target Mcl-1." (PMID 23284704, 2012). "This makes the exploration of combination strategies crucial for improving current treatment of ABT-737 against cancer, of which the hot issue is to combine ABT-737 with other drugs which have the ability to modulate Mcl-1." (PMID 23284992, 2012). "In many tumors, miR-29c expression is decreased to different extent, which regulates MCL-1, TCL-1 and other cancer-related genes and other genes involved in tumor onset and progression." (PMID 23056289, 2012). "We further examined the potential role of other proteins, namely Mcl-1, XIAP and cIAP2 in the sensitivity of cancer cells to FL118." (PMID 23029106, 2012). "Our results showed that it was not only Bik but also Mcl-1 accumulation during the treatment of proteasome inhibitors, and combining proteasome inhibitors with Mcl-1 siRNA would enhance the ultimate anticancer effect suggesting this combination might be a more effective strategy for cancer therapy." (PMID 22078414, 2011). "Many groups also reported inverse correlations between cancer cell sensitivity to ABT-737 and Mcl-1 expression levels in many cancer types." (PMID 21949692, 2011).
cancer (continued). "It has been known that c-Myc renders cancer cells sensitive to TRAIL-induced apoptosis by the up-regulation of DR5, the activation of caspase-8, and the down-regulation of c-FLIP and Mcl-1." (PMID 21513580, 2011). "These miRNAs target the tumour suppressor genes, PTEN, TP53INP1 and TP53INP2, and other proteins involved in cancer development and progression, such as BCL2L2, ERBB4, MAPK9, MCL1, MYCN, VEGFA and VEGFR1." (PMID 20668671, 2010). "Hence, investigation of potential co-targeting of Mcl-1 and c-FLIP presents an important direction in anti-cancer studies." (PMID 39753884, 2025). "In addition, the demonstration that oncogenic PI3K/AKT signaling identifies cancers that are sensitive to co-targeting AKT and MCL1, suggests that rational therapeutic combinations with BH3 mimetics can drive cancer specific kill." (PMID 41438049, 2025). "Cancer cells lacking Gln-K604 exhibit overexpression of c-Myc and Mcl-1 and display resistance to chemotherapy-induced apoptosis." (PMID 40338031, 2025). "Although HER2-targeting drugs (e.g., trastuzumab and lapatinib) have been reported to regulate MCL1 activity via distinct mechanisms (transcriptionally or translationally) in other cancer types, their effects in GC cells have not been well studied." (PMID 40075071, 2025). "In summary, we demonstrated that the antiapoptotic protein MCL1 is essential for tumorigenesis of pHGGs and that BCL2L1 methylation acts as a potent pantumor predictor of AZD5991/S63845 response in several pediatric cancers, including but not limited to pHGGs." (PMID 39846250, 2025). "Cancer cells can evade MCL1 inhibition by upregulating untargeted pro-survival BCL2 family members, particularly BCLXL and BCL2A1, enabling continued survival despite MCL1 blockade." (PMID 41155156, 2025). "This is an important capability, as there is strong concern about patient resistance to Venetoclax that is thought to be mediated by changes in cancer cells’ dependencies from one BCL-2 family protein to another, for instance, from BCL2 priming to MCL1 priming." (PMID 40507334, 2025). "The question whether a direct targeting of c-FLIP and Mcl-1 with chemical compounds is more efficient for the particular anti-cancer treatment compared to downregulation of c-FLIP and Mcl-1 levels has to be addressed in the future studies." (PMID 39753884, 2025). "However, induction of BIM by MEK or KRASG12C inhibition alone is often insufficient to induce apoptosis in KRAS-mutant cancer cells because BIM is bound and neutralized by pro-survival BCL-2 family proteins such as BCLX-XL or MCL-1." (PMID 40316540, 2025). "Also, additive antitumor activity has been observed with gemcitabine and ABT‐737 in various cancers, where their combined effect disrupts the interaction between USP9X and Mcl‐1, enhancing apoptosis and potentially overcoming inherent drug resistance." (PMID 40405831, 2025). "However, when MCL-1 is bound by SAHBD, its anti-apoptotic activity is inhibited, thereby sensitizing the cancer cells to apoptosis triggered by death receptor stimulation." (PMID 39795861, 2024). "As a binding site for miR-29b was predicted within 3’UTR, which is identical for all MCL-1 isoforms, these studies suggest that the influence of miR-29b on the level of specific MCL-1 isoforms could be different in normal and cancer cells." (PMID 39695189, 2024). "Importantly, although mitochondrial function decreased in both cancer cell lines after IMQ treatment, mitochondrial function was still maintained at a relatively high level in Mcl-1-overexpressing cells." (PMID 39272918, 2024). "Induced myeloid leukemia cell differentiation protein (MCL1) is a crucial member of the B-cell lymphoma-2 (BCL2) family of apoptosis regulators, playing a significant role in maintaining cellular homeostasis and promoting cancer cell survival." (PMID 38371625, 2024).
cancer (continued). "This evidence suggests that the expression of Mcl-1 may play a significant role in IMQ-induced ROS generation, mitochondrial dysfunction, mitochondrial structure, mitophagy, and cell death in cancer cells." (PMID 39272918, 2024). "Taken together, these findings indicate that Mcl-1 overexpression may increase the mitochondrial OCR and increase mitochondrial capacity in cancer cells in order to endure physiological stresses." (PMID 39272918, 2024). "Combining chemotherapy with the silencing of BCL-xL significantly increased cancer cell death from less than 20% to 60–70%, while silencing MCL-1 or BCL-2 had no substantial impact on sensitivity to chemotherapy." (PMID 38898061, 2024). "Achieving selective inhibition of cancer cells without affecting healthy cells and tissues remains difficult, and many MCL1 inhibitors have short half-lives." (PMID 39802137, 2024). "In contrast, IMQ decreased the expression of mitochondrial fusion marker Mfn1 in BCC and AGS control cells but not in Mcl-1-overexpressing cancer cells." (PMID 39272918, 2024). "In some RS cases (e.g., RSVR3, RS1050, RS1316), MCL-1, BCL-xL, and BFL-1 exerted a prominent role in protecting cancer cells from apoptosis, suggesting their direct targeting might be effective and outperform BCL-2 antagonism." (PMID 38724507, 2024). "MCL1, which is a member of the BCL‐2 family, is overexpressed in many cancers." (PMID 38264936, 2024). "Unlike cancer cells, we did not observe any reduction in Mcl1 mRNA levels following the inhibition of B-Raf." (PMID 37108645, 2023). "Several ARGs showed gain of CNVs such as E2F1, MCL1, and PIK3CA across multiple cancers." (PMID 36937870, 2023). "Current efforts are aimed at developing effective and tolerable treatment schedules for the BH3-mimetic drugs that inhibit MCL-1 or BCL-XL and to discover which other anti-cancer agents can be combined with these drugs to achieve effective and safe cancer therapy." (PMID 36342579, 2023). "Most types of cancer, including MM, avoid cell death by overexpressing diverse antiapoptotic proteins of the BCL‐2 family [e.g. B‐cell lymphoma 2 (BCL‐2), myeloid cell leukemia sequence 1 (MCL‐1) and B‐cell lymphoma extra‐large (BCL‐XL)]." (PMID 37704591, 2023). "In those types of cancer, MARCH5 may act as a tumor suppressor by inhibiting MCL1 overexpression, and a therapeutic strategy involving the use of BH3 mimetics could be paired with MARCH5 induction, in order to achieve cancer regression." (PMID 38139010, 2023). "MCL-1 was reported to positively regulate the OXPHOS and promote chemoresistance in cancer." (PMID 37919300, 2023). "Indeed, it was shown by the numerous studies that the mechanism of S63845 action in cancer cells is correlated with the release of pro-apoptotic proteins, such as NOXA, BAK and BIM, upon S63845 binding to the MCL-1 protein." (PMID 37108344, 2023). "Mcl-1, a member of the BCL-2 family, is among the most frequently amplified genes in cancer." (PMID 37601693, 2023). "It has been studied that the obstinacy of several kinds of cancer cells to ABT-737 may be due to ABT-737′s inability to target another prosurvival protein, Mcl-1." (PMID 36982637, 2023). "Importantly, previous research has demonstrated that in cancer cells that have constitutively active B-Raf (V600E) activates downstream STAT3, which in turn activates Mcl1 transcription, which is an antiapoptotic factor." (PMID 37108645, 2023). "Consequently, cellular expression of MCL-1 was reduced, promoting cell death in MCL-1-dependent cancer cells." (PMID 37684238, 2023).
cancer (continued). "However, consequent studies revealed that cancer cells can acquire resistance to ABT-737 and ABT-199, which is partially mediated by the up-regulation of MCL-1, another member of the BCL-2 family." (PMID 37108344, 2023). "It is thus evident that irrespective of the kind of conventional therapeutic agent, cancer cells tend to upregulate Mcl-1 to block cell death ensuring cell survival." (PMID 36045907, 2022). "Targeted downregulation of Mcl-1 reinstated the sensitivity of cancer cells towards ABT-737, suggesting that Mcl-1 is a major resistance factor against ABT-737 and its derivatives and that suppressing Mcl-1 expression or its pharmacological inhibition would yield a much better clinical outcome." (PMID 36045907, 2022). "In many cancers, high levels of anti-apoptotic proteins such as Bcl-2, Bcl-xL and Mcl-1 were shown to contribute, not only to lack of response to chemotherapy, but also to tumor initiation and progression." (PMID 35265218, 2022). "Inhibitors of Bcl-2 and Mcl-1 can increase the frequency of DiM of normal fibroblasts (but not of cancer cells) but duration of mitotic arrest does not change in these cases." (PMID 36188556, 2022). "Our direct observations using specific inhibitors demonstrate that only normal human fibroblasts are sensitive to inhibition of Mcl-1, while four cancer cell lines are not." (PMID 36188556, 2022). "Since the phenotype of so-called cancer stem-like cells (CSCs) is a known feature of many chemotherapy-resistant tumors, it was then investigated whether MYC and MCL1 contributed to the enrichment of CSCs." (PMID 36501221, 2022). "Cancer cells can suppress apoptosis by the overexpression of anti-apoptotic proteins (e.g., B-cell lymphoma-2 (BCL-2), BCL-XL, and myeloid cell leukemia-1 (MCL-1)) to downregulate or inactivate pro-apoptotic proteins (BCL-2-associated X, BCL-2-associated K, and BCL-2-related ovarian killer)." (PMID 36627891, 2022). "More importantly, targeting MCL-1 using AT-101 inhibited PEL development in xenograft tumor models, suggesting that MCL-1 inhibitors may serve as effective novel anti-cancer therapeutics for PEL." (PMID 33471866, 2021). "Our data demonstrate that ANO1 expression facilitates the expression of MCL1 and regulates the expression, subcellular distribution and proteolytic degradation of p27Kip1, which may explain how ANO1 mediates cancer cell progression." (PMID 33803266, 2021). "In this study, we found that pharmacological inhibition and knockdown of BMI-1 increases apoptosis in cancer cells, but not in normal cells, and induces downregulation of Mcl-1 protein expression via the ubiquitination pathway." (PMID 34576269, 2021). "The anti-cancer effects of miR-193a-3p are precluded by the repression of multiple target genes, including cancer related genes such as CCND1, KRAS, RASSF1, STMN1, and MCL1." (PMID 33747358, 2021). "The stabilization of MCL-1 (myeloid cell leukemia 1), a pro-survival protein, is promoted by the hyper-activation of the PI3K/AKT pathway as a result of PTEN downregulation in miR-21-overexpressed cancer cells." (PMID 34066762, 2021). "Whilst BCL-XL, MCL-1 and BCL-2 have received most of the attention in oncology drug development, the lesser discussed pro-survival BCL-2 proteins, BCL-W and BFL-1, also have important roles in cancer." (PMID 34581776, 2021). "Validation that amplified MCL-1 is the contributing factor in cancers came when knockdown of MCL-1 led to a significant reduction in cell growth in MCL-1-amplified cell lines, but not MCL-1-unamplified lines." (PMID 33799592, 2021). "Moreover, the expression levels of Mcl-1 and DUB3 were decreased by PTC596 in all tested cancer cell lines." (PMID 34576269, 2021).
cancer (continued). "This anti-apoptotic activity contributes to cancer development and also resistance to chemotherapy, as cancer cells often control the death mechanisms by elevating the expression of BCL-2, BCL-XL, and MCL-1, which neutralises the apoptotic action of the BH3-only proteins of the BCL-2 family." (PMID 34680203, 2021). "Levels of BCL-2 are also generally decreased following BETi treatment, though notably, other pro-survival proteins including BCL-XL, MCL-1 and BFL-1 have been shown to be reduced in different cancer types, leading to a further reduction in the apoptotic threshold of the cell." (PMID 33799592, 2021). "Other STAT target genes are involved in cancer signaling to regulate cell proliferation (e.g., cyclin D, HSP90), apoptosis (e.g., BCL-2, MCL-1, Bcl-xL), angiogenesis (e.g., VEGF-A, FGF), metastasis (e.g., MMP1-3, Vimentin, ICAM-1) and signaling (e.g., AKT, PI3K, TNF-R2)." (PMID 34439323, 2021). "Amplification of the apoptotic inhibitors Bcl-2-like genes, MCL-1 and BCL-XL, and deletion of apoptotic-promoter genes BOK and PUMA are presented in the somatic copy number variations in over 3000 cancer specimens across 26 human cancer types." (PMID 34142021, 2021). "Cancer cells, including HNSCC, may hijack these processes by overexpressing MCL1, and thus promote cell survival." (PMID 33803266, 2021). "As the clinical development of MCL-1 selective inhibitors progresses, MCL-1 selective inhibitors may become a new class of anti-cancer drugs that will bring clinical benefits to patients with a variety of hematologic malignancies and solid tumors." (PMID 33883020, 2021). "Mcl-1, along with other proteins such as BCL-2 and BCL-XL, are anti-apoptotic members of the BCL-2 family and have been shown to promote cell survival, chemotherapeutic resistance and are frequently dysregulated in a variety of human cancers." (PMID 33627786, 2021). "WIP1 (PPM1D) has a significant anti-apoptotic effect on uLMS, whereas BCL2 or MCL-1 appear to play little or no role in this cancer cell type." (PMID 35008180, 2021). "Use of MCL-1 (myeloid cell leukemia-1) as a biomarker and target for cancer prognosis and treatment has more publications than the publications from the use of XIAP as a biomarker and target in the cancer field." (PMID 34384473, 2021). "Since our results indicate that low concentrations of PTC596 (10 nM) increased cancer cell apoptosis through BMI-1-dependent Mcl-1 downregulation, we ruled out the effect of PTC596 as a novel small-molecule tubulin binding agent." (PMID 34576269, 2021). "Taken all together, we suggest that the ubiquitin–proteasome pathway-mediated Mcl-1 downregulation and miR-216a-5p-mediated DR5 upregulation have a critical role in autophagy inhibitor (lucanthone)-mediated sensitization of cancer cells to TRAIL-induced apoptosis." (PMID 35008442, 2021). "Small molecules called BH3 mimetics, that bind into the BH3 binding pocket of the prosurvival proteins BCL-2, BCL-xL, or MCL-1 (as BH3 domains of the proapoptotic ones do), favor mitochondrial apoptosis in cancer cells and have already useful clinical applications." (PMID 32722518, 2020). "Mechanistically, increased NOXA expression, observed upon antimitotic treatment, EMT or ER stress, is expected to modify dependence of cancer cells on BCL-2 family proteins, shifting the burden to support viability from MCL-1 (buffered by NOXA) to BCL-xL exclusively." (PMID 32722518, 2020). "We first explored the mRNA expression of MCL1, SRC, and Cofilin1 (CFL1) across cancers in the TCGA and Australian Pancreatic Genome Initiative (APGI) to identify contexts where a dual MCL-1, and SRC inhibitor strategy may be effective." (PMID 31735913, 2020). "As cancer cells frequently rely on the complementary activities of BCL-xL and MCL-1 for their survival we propose that the paracrine effects of paclitaxel, through IFN/TNF dependent NOXA induction, enhance BCL-xL dependency by decreasing the influence of MCL-1." (PMID 31937780, 2020).